PAGE4 (PAGE family member 4)
Description:
Intrinsically disordered protein that potentiates the transcriptional activator activity of JUN. Protects cells from stress-induced apoptosis by inhibiting reactive oxygen species (ROS) production and via regulation of the MAPK signaling pathway.
Synonyms: PAGE-4; GAGEC1; JM27; CT16.7; GAGE-9; JM-27; PAGE-1
Tractability: No criterion of Open Targets' tractability assessment is met for any kind of drug.
Gene: Protein-coding gene on chromosome X (49,793,653 to 49,834,264, forward strand). Ensembl gene ENSG00000101951.
Subcellular location: Cytoplasm; Nucleus; Mitochondrion
Subcellular location (Human Protein Atlas): Vesicles; Golgi apparatus
Gene Ontology:
Molecular function: DNA binding; nucleic acid binding; protein binding; transcription coactivator activity
Biological process: intracellular signal transduction; negative regulation of apoptotic process; negative regulation of reactive oxygen species biosynthetic process; response to starvation; regulation of stress-activated MAPK cascade; positive regulation of DNA-templated transcription
Cellular component: cytoplasm; mitochondrion; nucleus
Homologues: Orthologues: chimpanzee PAGE4 (100% identical), macaque PAGE4 (92% identical), pig PAGE4 (61% identical). Paralogues in human: PAGE2B (44% identical), PAGE5 (44% identical), PAGE3 (43% identical), PAGE2 (41% identical), XAGE5 (41% identical), XAGE3 (40% identical), GAGE10 (37% identical), GAGE1 (36% identical), GAGE13 (36% identical), GAGE2A (36% identical), GAGE12J (35% identical), PAGE1 (35% identical), and 10 more.
Diseases named in the same sentence as PAGE4 in open-access papers:
PAGE4 is named in the same sentence as 17 diseases in open-access papers, as found by Europe PMC text mining. Sharing a sentence is not in itself a finding about the gene and the disease. The quoted sentences say what the papers report.
prostate carcinoma (12 papers, 2011 to 2025). A carcinoma that arises from epithelial cells of the prostate gland. "Expression of PAGE4 is upregulated in primary prostate tumors and was found to be associated with a reduced risk of prostate cancer recurrence and a favorable prognosis." (PMID 38596293, 2024). "PAGE4 is a member of the Cancer Testis Antigen family and shows protective effects on prostate cancer cells against OS-caused cell apoptosis by attenuating DNA damage." (PMID 38166604, 2024). "Prostate-associated gene 4 (PAGE4) is an IDP that is expressed exclusively in adult males who have prostate cancer." (PMID 30909517, 2019). "Prostate-associated gene 4 (PAGE4) is an archetypal IDP implicated in human prostate cancer (PCa)." (PMID 30813315, 2019). "Previous studies have shown that KLK3 plays a critical role in inhibiting prostate cancer progression and restoring chemotherapy sensitivity, while PAGE4 has been reported to significantly enhance tumor cell responsiveness to gefitinib and other therapies." (PMID 41020875, 2025). "In cancer, the activation of the JNK/MAPK/ERK signaling pathway by PAGE4 promotes prostate cancer cell survival." (PMID 38538669, 2024). "Under oxidative stress conditions, PAGE4 has been shown to protect prostate cancer cells from reactive oxygen species-induced DNA damage and apoptosis." (PMID 38596293, 2024). "The PAGE4 is a remarkably prostate-specific tumor antigen that is upregulated in prostate cancer (PCa), and it is a stress-response protein that is upregulated in response to a variety of inflammatory stress." (PMID 37990040, 2023). "Accumulated evidences have shown that PAGE4 is reexpressed in pathological human prostate tissues, especially in symptomatic benign prostatic hyperplasia, as well as prostate cancer." (PMID 35633887, 2022). "We have previously shown that silencing PAGE4 expression inhibits cell survival and enhances chemo-cytotoxicity in prostate cancer cells." (PMID 30658679, 2019). "To investigate how PAGE4 is involved in oxidative stress protection in prostate cancer, we established inducible PAGE4-overexpressing cell lines, in which both mRNA and protein levels of PAGE4 were significantly increased by treatment of DOX." (PMID 30658679, 2019). "To illustrate these points, here, we use Prostate-associated gene 4 (PAGE4), an IDP implicated in prostate cancer (PCa) as an example." (PMID 30813315, 2019). "Phosphorylation by HIPK1 effectively disrupts the PAGE4 interaction with c-Jun and consequently stimulated c-Jun dependent transcription in prostate cancer cell models." (PMID 30909517, 2019). "Mechanistically, PAGE4 promoted the survival of prostate cancer cells through regulating MAPK pathway which reflected in decreasing the phosphorylation of MAP2K4, JNK and c-JUN but increasing phosphorylation of ERK1/2." (PMID 30658679, 2019). "A model for the PAGE4–Jun-Fos (AP-1)–AR regulatory circuit suggests phosphorylation patterns in prostate cancer cells can oscillate." (PMID 30909517, 2019). "Above all, the overexpression of PAGE4 in prostate cancer cell lines can protect cancer cells from cell death that is caused by oxidative stress through reducing DNA damage." (PMID 30658679, 2019). "In conclusion, the present study demonstrates the protective effects of PAGE4 in prostate cancer cells when exposed to oxidative stress." (PMID 30658679, 2019). "DNA damage and repair genes were previously reported to impact the metastatic potential of prostate cancer cells, here we found that cells overexpressing PAGE4 exhibited a gene expression pattern somehow of a low metastatic potential." (PMID 30658679, 2019). "We previously screened prognostic indicators of prostate cancer using tissue samples, and found that the transcription level of PAGE4 in prostate cancer tissues was negatively correlated with the biological recurrence of cancer." (PMID 30658679, 2019).
prostate carcinoma (continued). "It is reported that PAGE4 is expressed both in normal prostate and prostate cancer, but is also expressed in other male and female reproductive tissues including testis, fallopian tube, placenta, uterus, and uterine cancer." (PMID 21917134, 2011). "Modeling these changing transcription factor interactions in a cellular androgen control pathway suggested that the PAGE4 phosphorylation state could oscillate in time, which could result in temporal oscillations of androgen sensitivity in prostate cancer." (PMID 36671509, 2023). "Indeed, studies found that PAGE4 was upregulated when prostate cancer cells were exposed to various stress inducers (including inflammatory stress and oxidative stress)." (PMID 35633887, 2022). "Interestingly, the expression of PAGE4 was found to be significantly lower in androgen-resistant prostate cancer than primary prostate cancer." (PMID 30658679, 2019). "At the same time, another study indicated that the expression level of PAGE4 varied in prostate cancer tissues with different Gleason scores, suggesting that it might be used as an auxiliary indicator of prostate cancer malignancy." (PMID 30658679, 2019). "However, the exact functional role of PAGE4 in the context of signalling pathways under a diseased status of prostate cancer remains largely unclear." (PMID 30658679, 2019). "Having known that PAGE4 can protect prostate cancer cells from oxidative stress in vitro, we further investigated whether PAGE4 promotes tumor growth in vivo." (PMID 30658679, 2019). "Thus, the involvement of PAGE4 in diseased prostate, particularly in the prostate cancer, is somehow founded." (PMID 30658679, 2019). "Importantly, HIPK1 is expressed in both androgen-dependent and androgen-independent prostate cancer cells, whereas CLK2 and PAGE4 are expressed only in androgen-dependent cells." (PMID 30909517, 2019). "Furthermore, we examined the protein expression of PAGE4 and phosphorylated ERK1/2 in prostate cancer tissues." (PMID 30658679, 2019).
benign prostatic hyperplasia (3 papers, 2011 to 2022). A non-cancerous nodular enlargement of the prostate gland. "Furthermore, PAGE4 is known to be up-regulated in symptomatic benign prostatic hyperplasia (BPH) and in PCa." (PMID 21917134, 2011).
colorectal cancer (2 papers, 2014 to 2020). A primary or metastatic malignant neoplasm that affects the colon or rectum. "The aim of this study is to evaluate expression frequency of PAGE4, SCP-1, and SPANXA/D cancer testis antigen (CTA) genes as well as some clinical risk markers to predict liver metastasis of colorectal cancer patients." (PMID 26317029, 2014).
metastatic disease (2 papers, 2011 to 2017). "Consistent with the microarray data, all of the CTAs with the exception of PAGE4 were highly expressed in metastatic disease." (PMID 21917134, 2011).
breast carcinoma (1 paper, 2011). "These analyses identified more frequent CT expression in estrogen and progesterone receptor negative breast cancer, including NY-ESO-1, LAGE-1, MAGEA, PAGE4 and SSX1." (PMID 21437249, 2011).
colorectal tumor (1 paper, 2014). "The expression frequency of PAGE4, SCP-1, and SPANXA/D cancer/testis antigen (CTA) genes was obtained using reverse transcription polymerase chain reaction (RT-PCR) assay in 90 colorectal tumor samples including both negative and positive liver metastasis tumors." (PMID 26317029, 2014).
hyperplastic (1 paper, 2022). "The current study determined that PAGE4 was upregulated in hyperplastic prostate and it was mainly localized in the stromal compartment." (PMID 35633887, 2022). "PAGE4 was shown to be upregulated in human hyperplastic prostate and mainly located in the stroma." (PMID 35633887, 2022).
lymph node metastasis (1 paper, 2014). "Our results revealed that the expression of SCP-1 and PAGE4 was significantly correlated with lymph node metastasis (N category) (P < 0.05)." (PMID 26317029, 2014). "The classification accuracy rate of the model based on PAGE4 and lymph node metastases was 80.3% which surpassed the proportional by chance accuracy criteria, supporting the utility of the model." (PMID 26317029, 2014). "However, only two independent factors—PAGE4 and lymph node metastasis—were selected as candidate markers for establishing a panel to predict liver metastasis in CRC patients." (PMID 26317029, 2014). "In addition, using multiple logistic regression, we constructed a model based on PAGE4 and lymph node metastasis to predict liver metastasis of CRC." (PMID 26317029, 2014). "The association between CTA genes expression frequency and clinicopathological factors was also examined and our data showed that the expression of PAGE4 and SCP-1 was correlated with the presence of lymph node metastasis." (PMID 26317029, 2014). "All factors significantly correlated with liver metastasis (the frequency of PAGE4 and SCP-1 genes expression, depth of invasion, and lymph node metastasis) were taken into account for performing multiple logistic regression analysis." (PMID 26317029, 2014). "Although we verified the correlation between SCP-1 and lymph node metastasis, the lack of correlation between PAGE4 and lymph node metastasis was rejected in our dataset." (PMID 26317029, 2014).
metastatic cancer (1 paper, 2019). A carcinoma which has spread from the original site of growth to another anatomic site. "Additionally, the previous finding that PAGE4 protein was detected more often in localized PCa than metastatic cancer highlights again the reverse correlation between PAGE4 expression and cancer aggressive phenotype." (PMID 30658679, 2019).
Prostatic Intraepithelial Neoplasia (1 paper, 2018). "However, PAGE4 protein is highly expressed in the epithelial cells in Proliferative Inflammatory Atrophy (PIA) lesions and in high-grade Prostatic Intraepithelial Neoplasia (PIN) lesions, both of which are thought to be PCa precursors." (PMID 29914187, 2018).
tumor (11 papers, 2009 to 2025). "Thus, it is possible that PAGE4 blocks the development of aggressive PCa through attenuating the cell damage caused by oxidative stress which exists in the tumor microenvironment." (PMID 30658679, 2019). "PAGE4 is also upregulated in the primary tumor samples of CRC with liver metastasis and is suggested as a potential biomarker to predict liver metastasis in CRC." (PMID 38166604, 2024). "To test, we found that NAC treatment significantly inhibited the expression of PAGE4 in tumor tissues." (PMID 30658679, 2019). "When we treated the mice with antioxidant NAC, we found that the promoting effect of PAGE4 overexpression on tumor growth was partially impeded." (PMID 30658679, 2019). "In support, by analysing TCGA data, we found that patients with high expression of PAGE4 in tumor tissues had longer disease-free survival (DFS) time than those with low PAGE4 expression." (PMID 30658679, 2019). "Firstly, ROS induced PAGE4 expression, which in turn protected cells from apoptosis and DNA damage in vitro and promoted tumor growth in vivo." (PMID 30658679, 2019). "For example, low expression levels of PAGE4 coupled with the notorious tumor heterogeneity can make this treatment option challenging." (PMID 29914187, 2018). "Down-regulation was seen for CNTN1, CXCL13, MAOB, PAGE4, PENK, SPOCK3 in CP compared to NP as well as for HSD17B2, SALL1, TRPA1 for tumor-associated bladder stromal cells compared to normal bladder." (PMID 19737398, 2009). "In consistent with our previous finding that PAGE4 is a stress-response protein, we here confirmed that PAGE4 expression was remarkably induced by ROS stimuli not only in cell models but also in xenografted tumor tissues." (PMID 30658679, 2019). "In any rate, in this in vivo experiment, we observed the direct effect of PAGE4 overexpression on tumor survival, and we also confirmed that lowering ROS level in tumor tissue indeed decreased the expression of PAGE4, which nicely agrees with the stress-response role of PAGE4 to ROS." (PMID 30658679, 2019). "Consequently, the net result of NAC treatment on PAGE4 overexpressing-tumors would be the less cell survival, namely an impeded tumor growing." (PMID 30658679, 2019). "Immunohistochemistry was used to identify protein expression of PAGE4 in tumor tissues." (PMID 30658679, 2019). "T-cell lines generated from PCa patients using the agonist peptide showed high levels of lysis of PAGE4-expressing tumor cells and enhanced secretion of Interferon gamma (IFN-g), granzyme B, Tumor Necrosis factor alpha (TNF-a), Interleukin 2 (IL-2) and lymphotactin." (PMID 29914187, 2018). "Additionally, PAGE4 was found to promote tumor growth in vivo." (PMID 30658679, 2019). "In addition, PAGE4 overexpression promoted tumor growth in xenograft mouse models." (PMID 30658679, 2019). "Annotation of F3 as iCAF was further consistent with our recent study demonstrating expression of CES1 and PAGE4 by C1 prostate fibroblasts exhibiting an iCAF-like phenotype and in PIN and low Gleason tumours." (PMID 41378308, 2025). "In support, higher expression of PAGE4 predicted a better DFS of PCa in TCGA dataset, adhering to its inhibitory role of tumor aggressiveness." (PMID 30658679, 2019). "The frequency of PAGE4 and SCP-1 genes expression was significantly higher in the primary tumours with liver metastasis when statistically compared with primary tumors with no liver metastasis (P < 0.05)." (PMID 26317029, 2014). "Whilst the abundance of PAGE4+ or CES1+ cells did not significantly differ between these two tumor types, PAGE4+/CES1+ cells tended to accumulate in nests within intraglandular areas of stromogenic tumors." (PMID 41327318, 2025). "By all means, it is reasonable to speculate that the artificially enforced overexpression of PAGE4 in xenografted tumor would not completely mimic the pathological function of PAGE4 that is endogenously induced by microenvironmental ROS." (PMID 30658679, 2019).
tumor (continued). "However, when we checked the expression of several tumor less aggressiveness-related genes, such as ACTA2, FBLN1, F2R, we found that the expressions of these genes were increased upon overexpression of PAGE4." (PMID 30658679, 2019). "Finally, it is conceivable that tumour cell heterogeneity could lead to the emergence of PAGE-negative neoplastic clones, capable of escaping treatment-induced and PAGE4-specific immune surveillance." (PMID 29914187, 2018). "All of the CTAs with the exception of TTK, were significantly correlated with the prostatectomy Gleason score (CEP55; p = 0.0057, NUF2; p = 0.0051, PBK; p = 0.0295, PAGE4; p = 0.0236); however none were correlated with age, preoperative PSA and tumor stage." (PMID 21917134, 2011).
cancer (8 papers, 2012 to 2024). A tumor composed of atypical neoplastic, often pleomorphic cells that invade other tissues. "Some studies on other types of cancer also revealed similar results for the association of PAGE4 gene expression with aggressive phenotypes." (PMID 26317029, 2014). "Most recently, a prostate cancer associated antigen, PAGE4, was reported to inhibit stress-induced cell death." (PMID 23028975, 2012). "Clinically, the protection of PAGE4 on ROS stress may be translated into the less harmful DNA damage induced by ROS and therefore resulting in less chance to accumulate mutations to develop an aggressive cancer." (PMID 30658679, 2019). "In cellular process, we previously showed that PAGE4 mainly localized in mitochondria, and overexpressing PAGE4 protected cancer cells from different kinds of stress such as glucose deprivation, treatment of TNFα or chemical drug, through increasing the protein level of p21." (PMID 30658679, 2019). "In addition, several genes that were reported to be related to a less cancer aggressiveness or metastatic potential were found to be increased upon PAGE4 overexpression, including ACTA2, FBLN1 and F2R." (PMID 30658679, 2019). "Second, heterogeneity in PAGE4 expression could also impair immunogenicity and immune recognition of cancer cells by the immune system, resulting in decreased vaccination efficacy." (PMID 29914187, 2018). "Finally, it would be important to know if there is a link between PAGE4 and resistance to anti-cancer drugs, such as abiraterone or enzalutamide." (PMID 28362316, 2017). "Thus, a high expression of PAGE4 in PCa tissues may serve as a potential biomarker for better cancer prognosis." (PMID 30658679, 2019). "Considered together, our work highlights how coupling between Notch, EMT and PAGE4/AR signaling pathways can give rise to non-trivial dynamics and non-genetic heterogeneity in a cancer cell population." (PMID 33652914, 2021). "However, given that many metastatic PCa that are lack of PAGE4 expression are sensitive to ADT initially, it still could not be excluded that PAGE4 impacts cancer aggressiveness beyond ADT sensitivity." (PMID 30658679, 2019). "In such circumstance, PAGE4 may protect cancer cells through upregulation of p21 in most stress status with exception of H2O2, in which p21 level was not altered in either PAGE4-expressing cells or PAGE4-knocking down cells." (PMID 30658679, 2019).
PAGE4 also shares sentences with these, for which no sentence is quoted: gastric cancer (1 paper); liver (1); metastasis (1); prostate diseases (1); uterine cancer (1).